CD86 (CD86 molecule)
Diseases named in the same sentence as CD86 in open-access papers (continued):
Sharing a sentence is not in itself a finding about the gene and the disease.
tumor (continued). "Flow cytometric analysis showed that PJA1 knockdown significantly increased the infiltration of CD11c+ DCs and CD8+ T cells, as well as the proportion of CD86+CD11c+ tumour-infiltrating DCs." (PMID 38906860, 2024). "CTLA4 provides a negative modulatory signal to T cells interacting with its primary ligands, CD80 or CD86, on an antigen-presenting cell, and is well described as a key component of tumor immune evasion." (PMID 39478117, 2024). "Protein expression in mouse subcutaneous tumor tissue also suggested that CD86 protein expression was increased and CD163 expression was decreased after GJB2 knockdown." (PMID 39162005, 2024). "Specifically, CD80 and CD86 were higher in tumour-residing CCR7+ DCs, confirmed at a protein level, while Icosl was significantly higher in migrated CCR7+ DCs in the dLN." (PMID 38267413, 2024). "A stage-specific increase of CD80 expressing cells was recorded in CCH from the tumor bottom to the top, while CD86 was continuously and homogenously expressed at high levels." (PMID 39619201, 2024). "Although studies have shown the expression of CD80 and CD86 in tumor cells, the related studies are limited, and their relationship with prognosis is unclear." (PMID 37614091, 2024). "The correlation of CD86 and CD80 with clinical outcome in canine histiocytic disease has not been reported so far, however the expression of their receptor CTLA-4 on tumor cells is associated with a worse prognosis in other malignant tumors in dogs." (PMID 38962703, 2024). "A moderate correlation was found for mitotic count and CD80 (Spearman’s ρ = 0.49, p < 0.05) as well as mitotic count and CD86 positive tumor cells per mm2 (ρ = 0.34, p < 0.05)." (PMID 38962703, 2024). "They found that PE promoted the expression of MHC II and co-stimulatory molecules CD86 and CD80 on tumor-associated dendritic cell (TADCs), induced the production of IL-12 by TADCs, and enhanced the proliferation of both CD8+ T and CD4+ T cells." (PMID 39364399, 2024). "CD86 blockade alone improved RT-induced tumor control from 48% to 62%, with a fraction of the tumors initially responding, but later relapsing." (PMID 38349740, 2024). "Cytotoxic T lymphocyte associated protein 4 (CTLA4) is an immune-checkpoint molecule on T cells which interactes with CD80 (B7-1) and CD86 (B7-2) on tumor cells to inhibit the induction phase of the T cell response." (PMID 38439112, 2024). "Given that the immunosuppressive microenvironment impedes immunotherapy, we evaluated tumor-associated macrophages (TAMs) with different phenotypes: CD11b+F4/80+CD206+ (M2-like, immunosuppressive) and CD11b+F4/80+CD86+ (M1-like, pro-inflammatory)." (PMID 39339252, 2024). "Only CD86 expression was significantly higher in BCC as compared to cSCC for both the tumor core and the invasive front compartments." (PMID 39329753, 2024). "In contrast, the percentage of CD86 expressing tumor cells remained rather constant in all layers across the three stages, ranging between 91.1% and 98.9% expressing tumor cells." (PMID 39619201, 2024). "The expression of MHC class I, MHC class II, and CD86 in DC2.4 cells significantly increased after pulsing tumor lysates with VP-R8 compared to other treatments (p < 0.05)." (PMID 38892182, 2024). "Upon establishing the binding specificity of AYA22T-R2-13 to CTLA-4 on cytotoxic T lymphocytes (CTLs), our investigation aimed to uncover its potential in enhancing CTL-mediated tumor cell lysis by disrupting CTLA-4 interactions with the CD80 or CD86 axis." (PMID 38473398, 2024). "In the pre-treatment tissues, more stromal CD3 + FoxP3 + Tregs and CD86+/CD163 + macrophages were observed in patients with residual tumor existed in the resected lymph nodes (pN1), compared with patients with pCR." (PMID 38802821, 2024). "CD86 was also downregulated in all tumor models after treatment and further suggests a blunted dendritic cell maturation." (PMID 38727236, 2024).
tumor (continued). "Compared with NS group, significant upregulation of cd86 gene (symbol of mature DC) was detected due to activation by immunogenic antigens released by tumor cells after apoptosis induced by Nab-PTX, and by TLR signaling pathway sensitized by R837." (PMID 38594751, 2024). "Further evidence of immunosuppression after SOS1i+MEKi inhibition was indicated by increased PD-L1 on tumor cells and downregulation of CD86 on dendritic cells." (PMID 38727236, 2024). "CD40, which is expressed by both tumor cells and macrophages can cause the release of proinflammatory cytokines as well as CD80 and CD86 thereby resulting in augmentation of ant-tumor functions." (PMID 39003350, 2024). "Three tumor-associated macrophage (TAM) markers, MSR1/CD204, CD86, and CD68, exhibited a 6-fold (p < 0.0001), 8.9-fold (p < 0.0001), and 15.6-fold increase in mRNA expression levels, respectively, in LGG tumors." (PMID 38539537, 2024). "The CD86 total cell LI values were significantly higher in both the invasive front (p < 0.001) and tumor core (p < 0.001) of BCC cases as compared to cSCC cases." (PMID 39329753, 2024). "Sections of PGRN−/− tumor tissue showed a larger number of TAMs expressing pro-inflammatory markers, including iNOS, CD86." (PMID 38554213, 2024). "In an implanted mouse model of metastatic osteosarcoma, treatment with anti-PD-L1 antibody reduced the expression of PD-L1, increased the expression of CD80/CD86 in tumor cells, and increased the expression of CTLA-4 in tumor-infiltrating CD8+ T cells." (PMID 38542199, 2024). "We report significant findings on the beneficial impact of PD-L1 expression in tumor-infiltrating macrophages and the detrimental effects of CD86-positive macrophages on overall survival among patients treated with dendritic cell-based immunotherapy." (PMID 38791312, 2024). "Within the tumour specimens, the shIL37 group exhibited an increase in CD86 expression and a decrease in CD206 expression, along with a lower percentage of Ki67‐positive cells, when compared with the control and mock groups." (PMID 39500733, 2024). "(C) Geometric mean fluorescence intensity of anti-tumor markers (MHCII and CD86) and pro-tumor markers (CD163 and CD206) on macrophages from immuno-tumoroid cultures of CD47 knockout (KO) B16F10 cells." (PMID 38805560, 2024). "C002-treated tumors exhibited sustained IL-12 production with improved dendritic cells, monocyte-macrophage activity (MHCII, CD80/CD86 upregulation) and a polyfunctional Th1-cell response in the tumor infiltrates." (PMID 38895115, 2024). "blocks the interaction between CTLA4 and these ligands, CD80 and CD86, and keeps T cells remain active, which can recognize and kill tumor cells." (PMID 36949947, 2023). "The immunofluorescence staining of tumor sections showed that the expression of CD86 was significantly increased after PCMT1 knockdown, while the expression of CD206 was decreased." (PMID 37596654, 2023). "The maturation level of DCs (CD11c+/CD80+/CD86+) in the tumor-draining lymph nodes was first analyzed by flow cytometry." (PMID 37296221, 2023). "The binding of CTLA-4 to CD80/CD86 or PD-L1 to PD-1 suppresses T-cell activation, impairing tumour immune response and promoting a tolerogenic tumour microenvironment (TME)." (PMID 37460712, 2023). "The CD86 protein level was negatively associated with the CRC tumor differentiation and tumor node metastasis (TNM) stage, and was related to improved survival." (PMID 37726845, 2023). "By binding to B7-1 (CD80) and B7-2 (CD86) ligand on antigen-presenting cells, it regulates the activation of tumor-reactive T cells." (PMID 37834086, 2023). "PD-L1 (CD274) and CD86 (B7-2) are predominantly expressed on tumor cells or antigen-presenting cells in the TME." (PMID 37998737, 2023). "SBRT-treated TC-1 tumor cells co-cultured with DCs induced the highest percentage of CD11c+MHC-I+CD86+ mature DCs." (PMID 37833255, 2023).
tumor (continued). "Next, the mixed cells were stained with CD170 and CD11c to label AMs, CD86 to analyze AMs polarization, and Annexin V and PI for apoptosis analysis of tumor cells." (PMID 37951973, 2023). "Analysis of LCs from patient sentinel LNs has demonstrated that they are inefficient at priming naïve T cells, and we observed variable levels of CD86 on LC in tumor-draining LN." (PMID 37043573, 2023). "TAM-1s expressed high protein levels of major histocompatibility complex (MHC) class II, CD40, and CD86, suggesting a role in promoting anti-tumor adaptive immune responses." (PMID 37209684, 2023). "Results show that C3AR1 has the strongest correlation with M2 macrophages (CD163, MRC1, CD209), tumor-associated macrophages (CCL2, CD86, CD68) and monocyte immune markers, including (CD14, CD33, ITGAX)." (PMID 37005667, 2023). "CD86 as representative M1 marker was upregulated in coculture with CAFs and the two high secretor tumor cell lines HCT-116 and HT-29." (PMID 37947617, 2023). "Low expression of CD86+, overexpression of CD206+, and oncoprotein-induced transcript 3 (OIT3) in TAMs are significantly associated with tumor invasion abilities such as multifocal tumors and late-stage tumor lymph node metastasis (TNM)." (PMID 37663266, 2023). "In B16-F10 (melanoma) tumor-bearing mice, the time of day variation in CD86+ splenic macrophage frequency was lost, which suggests that systemic cues in tumor-bearing mice can alter circadian rhythms of macrophages in distal peripheral tissues." (PMID 37469718, 2023). "It is possible downregulated CD80 and CD86 expression in large A20 tumors is preventing the sustained CD28 signaling required for an effective adaptive anti-tumor response." (PMID 37016127, 2023). "Results showed that anti-IFN-γ treatment greatly down-regulated the CD86 expression level of tumor-infiltrating macrophages while up-regulated the CD206 expression of tumor-infiltrating macrophages." (PMID 37679802, 2023). "The immunofluorescence analysis of tumor tissue revealed that macrophages within the tumor express pro-inflammatory macrophage markers CD86 in testosterone-treated mice, but untreated mice display few pro-inflammatory macrophages." (PMID 37833789, 2023). "The most common mechanisms include the use of their major histocompatibility complexes as well as costimulatory molecules such as CD86 to enhance T-cell responses in the tumor microenvironment." (PMID 37111560, 2023). "The expression of NUPR1 was highly correlated with tumor‐associated macrophage markers including CCL2, CCR5, CD80, and CD86." (PMID 36468653, 2023). "In the TME of MC38 tumor‐bearing mice, treatment with QTPlus‐AM21 showed increased CD45+ tumor‐infiltrated immune cells and F4/80+ CD86+ M1 populations." (PMID 36412002, 2023). "In a Lewis-bearing mouse model, sophoridine (15 or 25 mg/kg) upregulated the expression of CD86/F4/80 in tumor tissues and significantly inhibited tumor growth." (PMID 37397472, 2023). "The proportion of CD86+ MDSCs in the spleen and blood after combination therapy was much higher than that in the tumor-bearing control group, and there was an increasing trend compared to the cryo-thermal therapy group." (PMID 37108179, 2023). "CD28 and CTLA4 expressed on T lymphocytes share identical ligands, CD80 and CD86, on tumor cells or antigen-presenting cells." (PMID 36983005, 2023). "A key component of tumor immunity is the expression of CD86+ on macrophages and dendritic cells, which are essential for antigen presentation to T cells." (PMID 36944686, 2023). "Not only the number of TILs is low but also the presence of receptors such as PD‐1 and CTLA4 on TILs can inhibit their antitumor effects after binding to ligands such as PD‐L1 and CD86 on tumor cells." (PMID 37088950, 2023).
tumor (continued). "Although CD80 and CD86 were highly expressed in multiple tumor-infiltrating lymphocytes, the lower proportions of tumor-infiltrating lymphocytes in the CT26 tumors as compared with the Hepa1-6 tumors made APC-mediated T cell activation less convenient." (PMID 37891570, 2023). "In vivo studies demonstrated that adoptively transferred ILC1s increased the macrophage CD86 expressing and inhibited the tumor growth, while depletion of ILC1s reached the opposite." (PMID 37679802, 2023). "The percentage of IRF8+ M-MDSC and TAMs and the expression of CD80 and CD86 in TAMs was increased in Pdcd1f/fLysMCre tumor-bearing mice compared to Pdcd1f/f tumor-bearing mice." (PMID 36581713, 2023). "This heightened CD86 expression positively correlates with the abundance of effector tumor-infiltrating lymphocytes under conditions of successful anti-PD-1 treatment." (PMID 38012715, 2023). "Common pathways of tumor growth (EGFR_network, Immune_inhibit_Oncogenic_pathways, and Radiotherapy_predicted_pathways) were compared between the high- and low-CD86-expression groups." (PMID 37064861, 2023). "In the MOC1 and MOC2 tumor models, the combination of metformin with a tumor vaccine increased the expression of CD86 and MHC-II, indicating an activated status of DCs." (PMID 37686159, 2023). "Dendritic cell presentation of tumor antigens to CD4+ and CD8+ T-lymphocytes is critical for tumor immunity, and CD86 has also been found to be a biomarker for a variety of tumor immune-related prognoses." (PMID 36674743, 2023). "The proportions of CD8+ T cells and CD86+ macrophages that penetrated the GBM tumour sites after imsEV treatment were also greatly increased." (PMID 37857647, 2023). "This group displayed higher expressions of PD-1, TNFRSF9, and CD86, along with increased enrichment scores for tumor marker pathways, distinguishing them from Cluster A patients." (PMID 38053840, 2023). "M1 macrophages express CD80, CD86, and HLA-DR surface markers and have anti-tumor effects by producing molecules such as IL-12, reactive oxygen species (ROS), and nitric oxide synthase (iNOS)." (PMID 38066642, 2023). "High expression of TNF-α, IL-1β, NOS2 and CD86 implied the polarisation of HF-CAR-PMs inside HER2+ tumours toward M1 phenotype." (PMID 37386139, 2023). "A significant (p < 0.01) upregulation of the CD11c+CD80+CD86+ cell (matured DC) proportion in tumour draining lymph nodes was detected after US+CA treatment compared to untreated tumours (26.40 ± 3.70% vs. 13.03 ± 2.03%)." (PMID 37631324, 2023). "The authors reported an increased expression of CD80 and CD86, meaning an increase in DC maturation, a tumor-inhibiting effect (tumor volume ≈ 0 mm3), and higher levels of INF-γ, TNF-α and IL-6." (PMID 37238966, 2023). "By real-time RT-PCR analysis, we observed that the expression of Cd80 and Cd86 tended to be lower in the tumor of S100a4-Cre; Ext1f/f mice and a significant difference in Cd80 expression was observed." (PMID 36809261, 2023). "This corresponded with the increased expression of PD-L1 as well as CD80 and CD86 molecules on the AT3OVA tumours." (PMID 37582853, 2023). "In tumors, PD-1 or CTLA-4 is expressed on CD8+ T cells and binds to PD-L1 or CD80/CD86 expressed on tumor cells and tumor-infiltrating myeloid cells (e.g., TAMs), respectively." (PMID 37345660, 2023). "F4/80 + macrophages with increased M1 marker CD86, activation marker iba-1 expression, and pro-inflammatory cytokine IL-1β production were detected in tumor tissue." (PMID 38001420, 2023). "Panobinostat also upregulated expression of the activating ligands CD80, CD86, and Nectin-2 in tumor cells, promoting NK cell cytolytic effect." (PMID 37090711, 2023). "The binding of CD80/CD86 on antigen-presenting cells to CTLA-4 on T-cells in the tumor microenvironment suppresses the immune system, enabling tumor proliferation." (PMID 37511453, 2023). "There was significant increase in CD11bhigh F4/80+ macrophages and M1 (CD11bhigh F4/80+ CD86+) in tumor." (PMID 38161697, 2023).
tumor (continued). "It was discovered that CD86 was significantly fewer in mouse tumor tissues injected with Calu6STK11KD cells compared with the counterpart." (PMID 37506141, 2023). "CTLA-4 blockade, i.e., the use of antagonist antibodies preventing CTLA-4 engagement by the natural ligands CD80 (B7.1) and CD86 (B7.2), was soon explored as a therapeutic target in tumor models by Allison." (PMID 36831435, 2023). "The pro-inflammatory phenotype (CD86) was expressed throughout the tumor in week 1, with a more evident higher concentration in the tumor edge region after 2 weeks." (PMID 36559209, 2022). "This further resulted in significantly increased proportion of CD86/MHC-II double-positive tumor Mo-MDSCs compared to transfer of PMEL T cells alone." (PMID 35476449, 2022). "Downregulated expression of CD86 and upregulated expression of CD24 was observed in tumour-associated Lin− population of most nsECT-treated mice." (PMID 36551739, 2022). "Interaction of CD86 with CTLA-4 inactivates T lymphocytes, causing the escape of tumor cells from the immune system." (PMID 35311155, 2022). "SAMHD1 silencing cooperated with radiotherapy to inhibit tumor growth and increase CD86+MHC-IIhigh M1 proportion and CD8+ T cell infiltration in vivo." (PMID 36578072, 2022). "In contrast, M2 macrophages, which have elevated expression of CD206 and reduced expression of CD80 and CD86, promote tissue repair and tumor cell proliferation and suppress antitumor immunity." (PMID 36442099, 2022). "This study showed that there was high expression of immunosuppressive molecules such as PD-L1, CTLA4 and CD86 in the tumour tissue of PCNSL." (PMID 36061189, 2022). "PSGL-1 and CD86 signals from monocytes were diminished during cancer progression, suggesting a less immunologically active tumor." (PMID 35493454, 2022). "Upon activation through Toll-like receptors (TLRs), DCs upregulate MHC and co-stimulatory molecules, including CD40 and CD80/CD86, all of which interact with T cells to promote a proinflammatory or anti-tumor response." (PMID 36248881, 2022). "The classically activated myeloid cell phenotype is characterized by expression of surface CD86, stimulation of anti-tumor immune responses, and production of pro-inflammatory cytokines." (PMID 35884700, 2022). "CAM-type macrophages express MHC II, CD86, NO, iNOS, showing the characteristics of pro-inflammatory response and anti-tumor, while AAM-type macrophages express IL-10, arg-1, CD206, CD163, TGF-β, showing immunosuppressive and tumor-promoting characteristics." (PMID 36439090, 2022). "Microenvironments of tumor nodules in HNSCC reveal an increased content of CD86+-activated and CD86+CD21-antigen-presenting B cells, as well as IgD-CD27+ memory B cells." (PMID 36143308, 2022). "Accumulating evidence indicates that tumor immune microenvironment (particularly regarding PD-1, PD-L1/2, forkhead box P3 (Foxp3), CD80, and CD86 expression) and immune checkpoint signaling play decisive roles in tumor immune evasion and growth." (PMID 36483592, 2022). "The 4T1 tumor cryosections from different treatment groups underwent immunofluorescence staining with CD86 and CD206 antibodies, which are predominantly expressed in M1-like TAMs and M2-like TAMs populations, respectively." (PMID 35812418, 2022). "We also observed high CD86 levels in the advanced tumor, which are supported by the presence of high CD86 B cell signatures in advanced stages of other cancers." (PMID 35626705, 2022). "During the first 7 days after resection, a high expression level of CD86 together with a low expression level of Arg1 were detected at the tumor resection site, indicating an inflammatory activation of the tissue infiltrating myeloid cells." (PMID 35884700, 2022).